RETN (resistin)
Diseases named in the same sentence as RETN in open-access papers (continued):
Sharing a sentence is not in itself a finding about the gene and the disease.
fractures (1 paper, 2008). "Bone variables such as number of vertebral fractures, low BMD in three of four measured sites, and the bone resorption marker ICTP also correlated to high resistin." (PMID 18234104, 2008).
gallstones (1 paper, 2014). Solid crystalline precipitates in the biliary tract, usually formed in the gallbladder, resulting in the condition of cholelithiasis. "Resistin protein expression was confirmed by western blotting in 13 patients with concomitant NAFLD and gallstone." (PMID 24559185, 2014).
glucose metabolic disorder (1 paper, 2013). "In a word, our results demonstrated for the first time that human resistin acted on cell cycle of myoblasts, inhibited myogenic differentiation, and promoted proliferation of myoblasts, which may be relevant to the glucose metabolic disorder." (PMID 23509781, 2013).
hantavirus infection (1 paper, 2018). "The present study shows that plasma resistin concentrations are elevated in the acute phase of PUUV hantavirus infection." (PMID 30517161, 2018).
hearing loss (1 paper, 2026). "We hypothesize that aortic stiffness and aortic blood pressure will be associated with hearing loss and attenuated by inflammatory biomarkers [matrix metalloproteinase-2 (MMP-2), resistin, and vaspin]." (PMID 41756249, 2026).
Hematuria (1 paper, 2018). The presence of blood in the urine. "High plasma resistin levels during the acute infection also associated with pronounced albuminuria and hematuria detected with urine dipstick test at hospital admission." (PMID 30517161, 2018). "When combining albuminuria and hematuria findings in the urine dipstick test (0–2+, 3–4+ or 5–6+), the higher the combined positive result, the higher was the maximum plasma resistin concentration." (PMID 30517161, 2018). "Plasma resistin levels in different categories of urine dipstick albuminuria and hematuria in 79 patients with Puumala hantavirus infection." (PMID 30517161, 2018).
human papillomavirus infection (1 paper, 2016). "Persistent human papillomavirus infection increases the resistin level in plasma of older women." (PMID 27549428, 2016). "However, the function of resistin in dengue virus and human papillomavirus infection is still unknown." (PMID 27549428, 2016).
hyperuricemia (1 paper, 2014). An abnormally high level of uric acid. "An in vivo study demonstrated that hyperuricemia may injure endothelial function via resistin-dependent mechanisms." (PMID 25371715, 2014).
intracerebral hemorrhage (1 paper, 2010). A cerebrovascular disorder characterized by bleeding into one or both cerebral hemispheres including the basal ganglia and the cerebral cortex. "Recently, we reported that high levels of resistin are present in the peripheral blood of patients with intracerebral hemorrhage and are associated with a poor outcome." (PMID 21029428, 2010). "Recently, we reported that high levels of resistin are present in the peripheral blood of patients with intracerebral hemorrhage and are associated with poor outcome." (PMID 21029428, 2010).
Lipedema (1 paper, 2025). Disorder of adipose tissue characterized by symmetric and bilateral enlargement of the lower extremities due to abnormal deposition of subcutaneous fat often in obese women. "Based on the common traits observed in obese patients, research up to date has focused on the analysis of adiponectin, leptin, visfatin, and resistin as potential biomarkers for lipedema." (PMID 40149538, 2025). "However, despite the accumulation of subcutaneous fat, the limited information that is currently available documents that women with lipedema have rather normal levels of adiponectin, leptin, visfatin, and resistin." (PMID 40149538, 2025).
Lipoatrophy (1 paper, 2014). Localized loss of fat tissue. "However, others found that resistin plasma levels were higher in lipodystrophic patients, being highest in those with isolated lipoatrophy." (PMID 24958357, 2014).
mood disorder (1 paper, 2025). A cognitive disorder a disturbance in which the person's mood is hypothesized to be the main underlying feature. "Further evidence highlights the potential utility of resistin as a biomarker of immune activation in mood disorders." (PMID 40507778, 2025).
mucinous adenocarcinoma (1 paper, 2010). An invasive adenocarcinoma composed of malignant glandular cells which contain intracytoplasmic mucin. "When compared control values, resistin levels were significantly higher in both patients' subgroups, while leptin levels were significantly lower only in the subgroup of patients with poorly differentiated (including the three patients with mucinous adenocarcinoma)." (PMID 21254741, 2010).
nematode infections (1 paper, 2015). "Finally, elevated resistin was associated with higher concentration of IL-6, CCL2 and TNFα and inflammatory factors, suggesting that the resistin/proinflammatory cytokine immune axis we identified in mice is also present in human nematode infections." (PMID 25568944, 2015).
nephritis (1 paper, 2008). Inflammation of renal tissue. "We demonstrated a positive correlation between resistin, creatinine, and ever having had nephritis and a negative correlation between resistin and GFR." (PMID 18234104, 2008).
non-alcoholic steatohepatitis (1 paper, 2014). "The relationship between resistin and non-alcoholic steatohepatitis (NASH) is not clear, some studies claimed that serum resistin levels were associated with neither the presence of NASH nor its severity, others declared that serum resistin was related with inflammation and fibrosis in NASH." (PMID 24559185, 2014).
obstructive sleep apnea syndrome (1 paper, 2010). Cessation of air flow during sleep due to upper airway obstruction. "The aim of this study was to investigate the relationship among plasma leptin, ghrelin, adiponectin, resistin levels, and obstructive sleep apnea syndrome (OSAS)." (PMID 20835311, 2010).
Opportunistic infection (1 paper, 2015). An infection that is caused by a pathogen that would generally not be able to cause an infection in a host with a normal immune system. "Further investigations are needed to understand whether high resistin levels among apparently healthy khat addicted subjects predisposes them for opportunistic infection if yes by which way?" (PMID 26448186, 2015).
osteonecrosis of the femoral head (1 paper, 2020). "Moreover, steroid-induced osteonecrosis of the femoral head (steroid-induced ONFH) is closely related to lipid metabolism level, so this study is intended to explore the relationship of RETN polymorphisms with susceptibility to steroid-induced ONFH in the Chinese Han population." (PMID 32143662, 2020).
ovarian dysfunction (1 paper, 2016). The inability of the ovaries to function. "In porcine ovaries resistin, the adipose tissue-specific secretory factor (ADSF) associated with ovarian dysfunction in obese women is known to upregulate PPARγ, which, in turn, reduces resistin expression." (PMID 27559343, 2016).
ovarian endometriosis (1 paper, 2023). A non-neoplastic disorder characterized by the growth of endometrial tissue in the ovaries. "The strengths of the study include the demonstration that the analysis of visfatin/NAMPT and resistin concentrations in the peritoneal fluid may be clinically useful in assessing the severity of inflammation in ovarian endometriosis." (PMID 38075048, 2023).
Ovarian Hyperandrogenism (1 paper, 2013). Increased production of androgens by the ovaries. "In human cultured theca cells, recombinant resistin triggered 17α-hydroxylase activity, a marker of ovarian hyperandrogenism in women with PCOS." (PMID 23680257, 2013).
pancreatic adenocarcinoma (1 paper, 2020). "Furthermore, pathway enrichment analysis showed that GTF2IRD1 may be involved in pancreatic adenocarcinoma pathway, TGF-β signaling pathway, T-cell receptor signaling pathway, leukocyte transendothelial migration, resistin as a regulator of inflammation." (PMID 32936232, 2020).
Paroxysmal atrial fibrillation (1 paper, 2023). Episodes of atrial fibrillation that typically last for several hours up to one day and terminate spontaneously. "The Framingham Offspring Study, in a long-term observation of a population of 2480 patients, assessed the impact of resistin concentrations on the occurrence of paroxysmal AF in the general population." (PMID 36624488, 2023).
Pleural effusion (1 paper, 2025). The presence of an excessive amount of fluid in the pleural cavity. "Our previous research confirmed that molecules such as LGALS9, MIF, and RETN were significantly elevated in the MPE of LCP compared to the pleural effusion of HP." (PMID 40959273, 2025).
primary aldosteronism (1 paper, 2024). An endocrine disorder characterized by excessive production of aldosterone by the adrenal glands. "Previously, we have shown an altered expression of different adipocytokines (leptin, adiponectin, resistin) both at circulating level and increased tissue expression in pathologies characterized by an increased cardiovascular risk (i.e., Primary Aldosteronism and Subclinical Cushing's Syndrome)." (PMID 38606379, 2024).
primary progressive-MS (1 paper, 2013). "In controls, there were positive correlations between circulating leptin and resistin with TNF-α and IL-1β in subgroup analysis, the highest levels of TNF-α, IL-1β, hs-CRP, resistin and leptin were observed in primary progressive-MS (PP-MS) patients." (PMID 24098530, 2013).
primary sclerosing cholangitis (1 paper, 2024). "The potential relevance of some genes in IBD has been supported by previous studies, such as RETN with increased resistin levels in CD and primary sclerosing cholangitis, the FLT3 receptor in a mouse model of chronic ileitis, and the therapeutic potential of IL-18 inhibition." (PMID 39165421, 2024).
rosacea (1 paper, 2020). A chronic erythematous skin disorder that affects the face. "Leptin, adiponectin, resistin, SERPINE1 and visfatin were also detectable in the SGs of rosacea-involved skin, suggesting that through the secretion of these adipokines, SGs may contribute to the development of the characteristic inflammatory milieu in rosacea." (PMID 33260746, 2020).
schistosomiasis (1 paper, 2019). An infectious disease caused by parasitic trematodes of the genus Schistosoma that colonize human blood vessels and release eggs that can cause granulomatous reactions leading to acute (swimmer's itch or acute schistosomiasis syndrome) or chronic disease. "Wami, evaluated the role of resistin and CRP in schistosomiasis in children 1–10 years old and CRP was observed to be one of the inflammatory biomarkers in children with schistosomiasis." (PMID 31856765, 2019).
senile cataract (1 paper, 2023). A cataract with no obvious cause occurring in persons over 50 years old. "Patients with senile cataracts, in turn, have been shown to have lower levels of resistin in the aqueous humor, relative to those in patients with retinal vein obstruction." (PMID 37892980, 2023).
spondyloarthritis (1 paper, 2021). "Interestingly, both serum levels of leptin and resistin were significantly higher as compared with the control group in patients with isolated knee OA and in cases combined with OA with other localization i.e., spondyloarthritis ± hip OA." (PMID 34440223, 2021).
systemic anaphylaxis (1 paper, 2023). "In this study, we demonstrate a potential role for resistin in glutenin-induced systemic anaphylaxis for the first time." (PMID 38139075, 2023).
teratoma (1 paper, 2021). A non-seminomatous germ cell tumor characterized by the presence of various tissues which correspond to the different germinal layers (endoderm, mesoderm, and ectoderm). "Although the amount of their production from the teratoma is unclear, these factors have been reported to circulate in wt serum on the order of ng/mL (Prl2c, resistin, insulin growth factor 2, angiopoietin, C1qtnf3, Postn, IGFBPs, PPBP), and pg/mL (colony-stimulating factor 1)." (PMID 33888706, 2021).
thyrotoxicosis (1 paper, 2016). A hypermetabolic syndrome caused by the elevation of thyroid hormone levels in the serum. "It has been reported that drug-induced hypothyroid rats exhibit elevated levels of adipose tissue resistin mRNA, which become almost undetectable after inducing thyrotoxicosis with exogenous T4 administration." (PMID 27637079, 2016).
triple-negative breast carcinoma (1 paper, 2020). An invasive breast carcinoma which is negative for expression of estrogen receptor (ER), progesterone receptor (PR), and human epidermal growth factor receptor 2 (HER2). "Immunostaining in triple-negative breast cancer samples showed that higher adipocytic TAZ/Resistin expression associates with higher clinical stages and poorer survival, demonstrating promising therapeutic targets." (PMID 33318171, 2020).
Urea (1 paper, 2022). "Urea increased ROS levels and expression of the adipokines retinol binding protein 4 and resistin." (PMID 35448889, 2022).
uterine tumor (1 paper, 2024). "Interestingly, resistin is also highly expressed in many of the vascular endothelial cell types and in metastatic uterine tumor cells, suggesting additional sources for this hormone in mouse lemurs." (PMID 38467625, 2024).
vasculitis (1 paper, 2021). "A significant correlation between chemerin level and five-factor score (FFS) was found (r = 0.320, p = 0.011), and resistin was correlated with both Birmingham vasculitis activity score and FFS (r = 0.256, p = 0.043 and r = 0.320, p = 0.011)." (PMID 34242326, 2021).
zoster (1 paper, 2016). "Overall, innate immune activation was minimal with zoster vaccination; resistin was the only inflammatory cytokine that significantly increased in the serum, and changes in gene expression were minor, which may explain why the influence of inflammatory genes on T cell responses was low." (PMID 27764254, 2016). "Innate immune activation was not very obvious with zoster vaccination; resistin, a member of the adipokine family, was the only inflammatory cytokine that significantly increased in the serum." (PMID 27764254, 2016).
cancer (113 papers, 2009 to 2026). A tumor composed of atypical neoplastic, often pleomorphic cells that invade other tissues. "Elevated resistin levels have been associated with an increased risk of cancer, particularly obesity-related cancers." (PMID 40002704, 2025). "Previous studies have investigated serum or plasma resistin levels in various cancers, finding a positive association with cancer risk." (PMID 40002704, 2025). "The primary secretion of resistin by adipose tissue and its role in inflammation have been linked to the promotion of chronic inflammation, which is a known risk factor for cancer." (PMID 39184804, 2024). "In in vitro experiments, resistin has been implicated in cancer resistance and an increase in cancer stem cells, and has been suggested to be a potential important target for cancer therapy." (PMID 38238841, 2024). "The 6636 people who were measured for resistin were followed for 15.4 ± 2.4 years, during which time 447 of them died; of these, 193 were deaths due to cancer, 108 due to cardiovascular causes, and 146 due to other causes." (PMID 36380110, 2022). "High levels of resistin are associated with less sensitivity to chemotherapy in different cancer types." (PMID 35890097, 2022). "Accumulating evidence has suggested a clinical association of circulating resistin with the risk of tumorigenesis and a relationship between blood resistin levels and the risk of cancer metastasis." (PMID 36497484, 2022). "High expression of resistin has been associated with visceral obesity, coronary artery disease, lung disease, and various cancers including breast, endometrial, and colorectal." (PMID 36077676, 2022). "Resistin is an inflammatory cytokine that has been associated with several pathological conditions and plays multi-faceted roles in cancer progression." (PMID 34572725, 2021). "While initial research focused on obesity and insulin resistance, resistin was later implicated in the occurrence and progression of various malignant tumors." (PMID 32420377, 2020). "We observed that higher leptin and resistin levels were associated with reduced risk of cancer mortality, an association that was restricted only to Blacks." (PMID 29662629, 2018). "In this prospective cohort, we examined the association between pre-diagnostic metabolic biomarkers, plasma adiponectin, resistin, leptin and lipoprotein (a), and the risk of cancer mortality." (PMID 29662629, 2018). "In race stratified analysis, among Blacks, higher resistin levels were associated with more than a 6-fold increased risk of cancer mortality with full adjustment (adjusted HR per SD log resistin: 6.68, 95% CI: 2.10-21.21)." (PMID 29662629, 2018). "Pre-diagnostic resistin levels were associated with a 6-fold increased risk of cancer mortality but only among Blacks." (PMID 29662629, 2018). "Other studies have also reported an association between higher leptin and resistin levels at diagnosis and increased cancer aggressiveness- defined as disease spread to sentinel lymph nodes - and higher stage at diagnosis." (PMID 29662629, 2018). "In conclusion, pre-diagnostic resistin and leptin levels are associated with risk of cancer mortality specifically among Blacks." (PMID 29662629, 2018). "Among Blacks only, each SD higher log-resistin was associated with a nearly 7-fold increased risk of cancer mortality (adjusted HR: 6.68, 95% CI: 2.10 – 21.21)." (PMID 29662629, 2018). "Resistin is not only associated with high grade cancers and survival of patients, research in recent years has raised the possibility of resistin playing a role in chemotherapy." (PMID 30131543, 2018). "Except for the study, the association between resistin levels and cancer risk was still significant (OR = 1.18, 95% CI = 1.09-1.28, I2 = 5.0%, P (for heterogeneity analysis) = 0.396)." (PMID 27509174, 2016).